PTPRD (protein tyrosine phosphatase receptor type D)
Diseases named in the same sentence as PTPRD in open-access papers (continued):
Sharing a sentence is not in itself a finding about the gene and the disease.
cancer (continued). "Along with numerous upregulated inflammation-related proteins, the downregulation in PTPRD and thus increased susceptibility to cancer development is consistent with previous studies demonstrating the important role of LAL in inflammation and immunosuppression." (PMID 37595802, 2023). "PTPRD/PTPRT mutations may be a potential biomarker for predicting ICI treatment responsiveness in multiple cancer types." (PMID 36248841, 2022). "Notably, fourteen DDR gene mutations were significantly more prevalent in PTPRD/PTPRT mutant cancer patients than in WT patients (all P < 0.001)." (PMID 36248841, 2022). "We found that PTPRD/PTPRT mutations were a favorable biomarker of pan-cancer ICI treatment." (PMID 36248841, 2022). "The PTPRD gene has been also associated with different cancer forms in humans." (PMID 31749836, 2019). "Furthermore, protein tyrosine phosphatase receptor type delta (PTPRD) at 9p23 region was associated with restless legs syndrome as well as cancers." (PMID 29765957, 2018). "We reviewed several genomic studies to define patterns of PTPRD loss in cancer." (PMID 25138050, 2014). "In other tumors, however, PTPRD alterations may be linked with cancer development and metastases, and reduced expression of PTPRD has been reported to be associated with poor prognosis." (PMID 25126591, 2014). "However, the pan-cancer association between PTPRD/PTPRT mutation and the efficacy of ICIs remains unclear across pan-cancer patients." (PMID 36248841, 2022). "However, the clinical pan-cancer significance of PTPRD/PTPRT mutations in treated with ICIs remains unknown." (PMID 36248841, 2022). "Thus, whether PTPRD mutations were a pan-cancer biomarker for ICIs was worthy of further investigations." (PMID 34615542, 2021). "In addition to HNSCC, PTPRD mutations are also widely observed in other cancer types." (PMID 26267899, 2015). "Future studies are needed to explore the potential molecular mechanisms/signalling pathways that link PTPRD and asprosin in cancer." (PMID 38339334, 2024). "Cancer cells secrete exosomes containing miR-19b-3p, which targets the protein tyrosine phosphatase receptor type D (PTPRD) in TAMs, inhibiting the dephosphorylation of STAT, thereby leading to M2-like polarization." (PMID 39144141, 2024). "PTPRD function is frequently inactivated by genetic and epigenetic alterations in GBM and other cancers, and is associated with poorer patient prognosis." (PMID 36923251, 2023). "We further explored the prognostic value of PTPRD mutation in another ICIs cohort (MSK, Cancer Cell 2018) as an independent external validation." (PMID 37602864, 2023). "PTPRD is a phosphatase involved in the JAK-STAT pathway and frequently inactivated in various types of cancers, and its deleterious alteration is associated with a lower survival rate and frequent metastasis." (PMID 37051524, 2023). "PTPRD belongs to a family of protein tyrosine phosphatases that are involved in the regulation of many normal and cancer cell processes such as adhesion, proliferation and migration by regulating multiple cellular signaling pathways." (PMID 36923251, 2023). "The most frequent mutations in a large panel of 1123 cancer-related genes in the overall population of RCC patients were VHL (51%), PBRM1 (35%), BAP1 (16%), KMT2D (15%), PTPRD (15%), and SETD2 (15%)." (PMID 37427096, 2023). "Several papers term PTPRD a “tumor suppressor” gene based on e.g., its abilities to alter cancer-related phosphorylation pathways." (PMID 37139308, 2023). "In this study, we systematically collected genetic and clinical data to analyze the association between PTPRD/PTPRT gene status and clinical response in pan-cancer patients treated with ICIs." (PMID 36248841, 2022).
cancer (continued). "In the Samstein cohort, the univariate analysis showed that cancer type, TMB, treatment type, and PTPRD/PTPRT mutations were statistically significant in predicting OS in patients receiving ICIs." (PMID 36248841, 2022). "In contrast, CXCR3, an anti-tumor receptor of ICIs, was shown to be upregulated in PTPRD/PTPRT mutant cancers (P <0.001)." (PMID 36248841, 2022). "Another subgroup analysis conducted based on cancer types showed that PTPRD/PTPRT mutant patients treated with ICIs had significantly longer OS than WT patients in NSCLC and SKCM, which is consistent with the results of previous studies." (PMID 36248841, 2022). "Second, most immuno-stimulators, such as MICB, MICA, CD80, ICOS, CD27, and various TNFSFs (all P < 0.05), were expressed at higher levels in PTPRD/PTPRT mutant cancers, compared with the WT." (PMID 36248841, 2022). "In line with the results of MSI sensor score, a higher MSI MANTIS score was found in PTPRD/PTPRT single-mutant or double-mutant cancers, compared with WT patients (P < 0.0001)." (PMID 36248841, 2022). "We analyzed the association between PTPRD/PTPRT mutations and patient outcomes using clinical data and genomic mutations from TCGA pan-cancer cohort." (PMID 36248841, 2022). "Other potential immune checkpoints, such as LAG3, CD96, PDCD1, BTLA, IDO1, and TIGIT, were also enriched in PTPRD/PTPRT mutant cancers." (PMID 36248841, 2022). "Most immune cells, including memory B cells, CD8+ T cells, Tfh, and macrophage M1 cells, were more abundant in PTPRD/PTPRT mutant cancer patients (all P < 0.05)." (PMID 36248841, 2022). "In this study, we performed a comprehensive analysis to evaluate the association between PTPRD/PTPRT mutations and the efficacy of ICIs across multiple cancers." (PMID 36248841, 2022). "Mutations in PTPRD, CREBBP, BRAF, NOTCH3, TERT, and SETD2, which are involved in various aspects of immune regulation, were reported as potential biomarkers in cancer patients after immunotherapy with improved survival." (PMID 36092890, 2022). "The PTPRD/PTPRT mutant cancer patients had a significantly higher MSI sensor score, compared with WT patients (P < 0.0001)." (PMID 36248841, 2022). "PTPRD or PTPRT are identified as tumor suppressor, which is frequently inactivated and mutated in various human cancers." (PMID 34123798, 2021). "This suggests that the PTPRD-ERK/STAT3-CXCL8 axis is the main pathway promoting cancer angiogenesis in PTPRD-inactivated cancers." (PMID 31805999, 2019). "Subsequently, we explored the anti-angiogenic effects of U0126 and S31–201 in cancer cells with stable PTPRD knockdown." (PMID 31805999, 2019). "Microarray analysis was used to identify differentially expressed genes in PTPRD-inactivated cancer cells." (PMID 31805999, 2019). "Initially, we identified this effect in cancer cells with stable PTPRD knockdown and we then confirmed it in wild-type GC cell lines." (PMID 31805999, 2019). "We found that metformin increased PTPRD expression in cancer cells, especially when PTPRD expression was downregulated." (PMID 31805999, 2019). "After assessing the efficacy of PTPRD knockdown by shRNA, we determined that stable knockdown of PTPRD increased cellular proliferation, as well as cancer cell migration and invasion, most likely via STAT3, as previously reported." (PMID 31805999, 2019). "Protein tyrosine phosphatase receptor delta (PTPRD) is frequently inactivated in various types of cancers." (PMID 31805999, 2019). "PTPRD has also been found to be mutated in CRC and in various other cancer types and is frequently inactivated by copy number loss in a broad range of cancer types." (PMID 30200630, 2018). "PTPRD regulates adhesion and migration of cancer cells in cooperation with β-catenin/TCF signaling, and its loss promotes cancer progression." (PMID 29844865, 2018).
cancer (continued). "Through integrative analysis of cancer genetic and clinicopathological data, deleterious alterations in PTPRT/PTPRD were associated with bevacizumab resistance, as indicated by a poor response rate and shorter survival." (PMID 30200630, 2018). "Although PTPRD inactivation is highly prevalent in various human cancers, its specific contribution to tumorigenesis remains poorly understood." (PMID 29228728, 2017). "The PTPRD gene is frequently subject to cancer-specific epigenetic silencing via promoter CpG island DNA hypermethylation." (PMID 26079428, 2015). "Our analysis of TCGA data indicates that nearly half of HNSCC tumors harbor a copy number alteration of PTPRD and that copy number loss is more frequent than copy number gain in HNSCC and across nearly all cancers analyzed." (PMID 26267899, 2015). "We analyzed data from The Cancer Genome Atlas (TCGA) and our previous whole-exome sequencing study and summarized the mutation, methylation, and copy number status of PTPRD in HNSCC and other cancers." (PMID 26267899, 2015). "PTPRD is a member of the Protein Tyrosine Phosphatases (PTPs) that is involved in various biological processes in cancer." (PMID 26474282, 2015). "Future studies are needed to further explore the potential molecular mechanisms/signalling pathways that may link PTPRD and asprosin in cancer." (PMID 38339334, 2024). "PTPRD is often inactivated via deletion or epigenetic mechanisms in several cancers." (PMID 36660927, 2023). "A high frequency of gene deletions of PTPRD occurs in a variety of cancers." (PMID 37602864, 2023). "In addition, reduced expression of PTPRD was correlated with invasive status of other cancers with highly activated WNT signaling." (PMID 37164978, 2023). "PTPRD/PTPRT mutations are common mutations in multiple cancer types, but there have only been a few studies that have been conducted on the role of this type of mutations in pan-cancer patients treated with ICIs." (PMID 36248841, 2022). "Similarly, a higher TCR Shannon Score was observed in the PTPRD/PTPRT single-mutant or double-mutant cancers, compared with WT patients (P < 0.01)." (PMID 36248841, 2022). "Overall, the results of this study demonstrated that PTPRD/PTPRT mutations are correlated with a poor prognosis and that PTPRD/PTPRT mutations might act as a pan-cancer biomarker for the prediction of ICI treatment efficacy." (PMID 36248841, 2022). "Notably, the significant upregulation of MHC I molecules was observed in PTPRD/PTPRT mutant cancers." (PMID 36248841, 2022). "Mutations in PTPRD restrict its ability to regulate STAT3, which promotes cancer progression." (PMID 34503185, 2021). "Assuming PTPRD inactivation is one of the driving events in cancer initiation, activating PTPRD by metformin may hinder cancer growth in many different ways." (PMID 31805999, 2019). "Additionally, metformin was found to efficiently inhibit PTPRD-loss-induced angiogenesis, decrease cell viability in PTPRD-inactivated cancers, and reverse the decrease in PTPRD expression." (PMID 31805999, 2019). "Based on our results, we conclude that metformin may be an attractive treatment option for PTPRD-inactivated cancers." (PMID 31805999, 2019). "More intriguingly, we discovered that metformin could reverse the decreased PTPRD expression in cancer cells." (PMID 31805999, 2019). "Therefore, in this study, we aimed to investigate the role of PTPRD in GC, with a focus on its role in cancer metastasis." (PMID 31805999, 2019). "Hence, we propose that the therapeutic efficacy of metformin in PTPRD-inactivated cancers should be further investigated." (PMID 31805999, 2019).
cancer (continued). "Protein tyrosine phosphatase receptor-type δ (PTPRD) is frequently inactivated in human cancers." (PMID 29228728, 2017). "PTPRD is one of the most frequently inactivated genes across human cancers." (PMID 27738328, 2016). "These researches indicated that the methylation of CpG in the PTPRD promoter was might be involved in the inactivation of PTPRD in many types of human cancers." (PMID 25412184, 2014). "Despite the potential role of PTPRD loss in cancer, Ptprd deficient mice do not spontaneously develop tumors." (PMID 25138050, 2014). "In addition, parkin (PARK2), ataxia telangiectasia mutated (ATM), phosphatase and tensin homolog deleted on chromosome 10 (PTEN), and receptor-type tyrosine-protein phosphatase delta (PTPRD) have been demonstrated to be critical targets in the development of cancers and neurodegenerative diseases." (PMID 38592583, 2024). "miR-324-5p via PTPRD/CEBPD axis could participate in the progression of cancer via VEGF." (PMID 36035118, 2022). "Additionally, we showed that metformin may be an efficient strategy for the treatment of PTPRD-inactivated GCs, as it efficiently inhibited cancer angiogenesis and growth and reversed the decrease in PTPRD expression." (PMID 31805999, 2019). "Therefore, the use of metformin may be an effective strategy in the treatment of PTPRD-inactivated cancers, as it not only reduces cellular proliferation, but also decreases angiogenesis in those cancers." (PMID 31805999, 2019). "Interestingly, head and neck SCC cells containing a PTPRD mutation were more susceptible to a STAT3 inhibitor, suggesting that use of this type of anti-cancer drug could be utilized for more successful treatments of head and neck SCC patients." (PMID 30208623, 2018). "No significant changes in the expression of protein tyrosine phosphatase receptor type D (PTPRD) and olfactory receptor family 4 subfamily M member 1 (OR4M1) were observed amongst those with EC versus non-cancer controls (P=0.044 and P=0.221, respectively)." (PMID 40902078, 2025). "In the present paper, we provide a detailed map of the gene and protein expression of PTPRD in health and disease (i.e., in EC and GBM cancers) using a combination of in silico, in vitro, and clinical sample data." (PMID 38339334, 2024). "Further studies will be needed to uncover the role of PTPRD in MPNST-G2 tumors and cancer cell migration." (PMID 37164978, 2023). "First, the enrichment levels of 29 immune signatures were evaluated between PTPRD/PTPRT mutant and WT cancers." (PMID 36248841, 2022). "On the other hand, inhibition of negative regulators such as PIAS3, SOCS1 and 3 and several cellular phosphatases (SHP1 and 2, PTPRD, PTPRT, PTPN1 and 2, DUSP22) can also lead to STAT3 activation in cancer." (PMID 35145111, 2022). "PTPRD and PTPRT (PTPRD/PTPRT) are the phosphatases of JAK-STAT signaling, a critical pathway in anti-cancer immunity regulation." (PMID 36248841, 2022). "As PTPRD-inactivated cancers are more dependent on ERK and STAT3 signaling, it seems plausible that PTPRD-inactivated cancers are more vulnerable to metformin due to its inhibition of both critical signaling pathways." (PMID 31805999, 2019). "In total, 91 genes were upregulated while 21 showed lower levels of expression, 12 of them were cancer-related genes: two deleted (CDKN2A and PTPRD) and nine amplified (EGFR among others)." (PMID 31703248, 2019). "This region also contains two other genes, PTPRD and DOCK8, that have been proposed as TSGs in other cancers." (PMID 26205786, 2016). "While most of these genes’ precise role in regulating STAT3 is not well-defined, it was shown that tyrosine phosphatase PTPRD can dephosphorylate STAT3 in cancer cells." (PMID 39985075, 2025).
cancer (continued). "The most prominent candidate on the role in the regulation of STAT3 phosphorylation by Sestrins that appeared in our search was the protein tyrosine phosphatase receptor delta (PTPRD), whose inhibitory effect on STAT3 phosphorylation in different cancer types was demonstrated in several studies." (PMID 39985075, 2025). "Collectively, our data suggest that PTPRD may have potential as a biomarker for malignancies such as EC and GBM, further implicating asprosin as a potential metabolic regulator in these cancers." (PMID 38339334, 2024). "In addition, the MSI sensor score was significantly higher in the PTPRD and PTPRT double-mutant cancers than in the single-mutant cancers (P < 0.0001)." (PMID 36248841, 2022). "Importantly, higher PD-L1 and CTLA4 expression levels were observed in the PTPRD/PTPRT mutant cancer patients, compared with WT patients, suggesting that ICI treatment is more applicable for PTPRD/PTPRT mutant cancer patients." (PMID 36248841, 2022). "The following most altered cancer genes were LRP1B (26%), PIK3CA (24%), CDKN2A (24%), PTPRD (15%), RB1 (13%), PDE4DIP (13%), PCLO (11%), KRAS (11%), FAT1 (10%), and RELN (10%), and these results partially overlap with the most altered genes depicted in the experimental cohort." (PMID 35330454, 2022). "Finally, the nomogram model based on the four factors, cancer type, TMB, treatment type, and PTPRD/PTPRT gene status, indicated a good accuracy in predicting the 1-, 3-, and 5-year survival of pan-cancer patients treated with ICIs." (PMID 36248841, 2022). "Examples of cancer related genes in the network included GAS6, MAP3K4, PRKD1, PTPRD, and VEGFA." (PMID 34434222, 2021). "Additionally, prospective trials incorporating tissue or ctDNA PTPRD phosphatase-mut as a biomarker are worth conducting both in NSCLC and other cancer types." (PMID 34615542, 2021). "Therefore, metformin appears to exert its effect on cancer cells not only by inhibiting ERK and STAT3 signaling, but also by reversing the downregulated PTPRD expression." (PMID 31805999, 2019). "As the loss of PTPRD activated both ERK and STAT3 signaling, a single specific inhibitor would not suffice in patients with PTPRD-silenced cancer." (PMID 31805999, 2019). "The exogenous expression of PTPRD in human GBM and other cancer cell lines inhibited cell growth, which coincided with a substantial decrease in the expression levels of phosphorylated STAT3 (Y705) and, consequently, one of its downstream targets, suppressor of cytokine signaling 3 (SOCS3)." (PMID 30208623, 2018). "This suggests that the scarcity of PTPRD and WWOX genes might have played an important role in progression of HNSCC, and could be considered as a target for cancer therapy or a biomarker in molecular pathology." (PMID 27501229, 2016). "PTPRD, as a natural antagonist of AURKA, might be of therapeutic value in cancers where its inactivation is epigentically reversible, such as in instances of promoter region hypermethylation." (PMID 22305495, 2012). "In this regard, the FDA-approved ramucirumab may not be effective in PTPRD-inactivated cancers, as previously reported." (PMID 31805999, 2019). "Moreover, co-deletion of PTPRD and CDKN2A occurs across a number of cancer types." (PMID 25138050, 2014). "The results demonstrated that the TCR Richness Score was notably higher in both the PTPRD/PTPRT single-mutant and double-mutant cancers, than in WT patients (P < 0.001), while there was no statistical difference between PTPRD/PTPRT single-mutant and double-mutant patients (P > 0.05)." (PMID 36248841, 2022). "Second, there were cases in TCGA tumors and CCLC cancer cell lines in which JAK2 was deleted in the absence of CDKN2A/CDKN2B or PTPRD deletion, suggesting that JAK2 deletion alone may have a functional benefit to cancer cells." (PMID 28977839, 2017).